MYD88 (MYD88 innate immune signal transduction adaptor)
Diseases named in the same sentence as MYD88 in open-access papers (continued):
Sharing a sentence is not in itself a finding about the gene and the disease.
tumor (continued). "The actions of MyD88 in regulating the expression of these factors is likely to involve both direct and indirect mechanisms, mainly coordinating the interplay between NF-κB, HIF1α, and STAT3 transcription factors, which are well known for its roles in tumor development and inflammation." (PMID 28662055, 2017). "Thus, research into immunotherapy targeting TLR4/MD-2 complex-mediated MyD88/NF-κB and Akt pathways of EOC cells will probably become focused on an approach to combination immunotherapy that simultaneously intensify anti-tumor immune responses while reversing tumor immune suppression." (PMID 27118139, 2016). "MyD88 KO mice have defects in TLR signaling and our results show that zVAD-fmk did not further retard growth of B16 tumors treated with RT, DTIC and HT in these mice, again indicating that HMGB1 in vivo is a key player in zVAD-fmk-induced anti-tumor immune responses." (PMID 25973681, 2015). "Tumor cells may generate DAMPs, TLR ligands, activating the TLR/MyD88/NFκBpathway." (PMID 25659093, 2015). "Tumor tissue derived DNA treatment did not affected the genes of TLR9 MYD88 pathway." (PMID 26133168, 2015). "However, zVAD-fmk did not further reduce tumor growth in MyD88 KO mice, mice treated with apyrase or RAG KO mice." (PMID 25973681, 2015). "MyD88 negative EOCs in contrast lack MyD88 and may represent more differentiated tumours that are less biologically aggressive." (PMID 24977712, 2014). "Taken together, the present studies demonstrated that tumor-derived autophagosomes (DRibbles) efficiently induced B cells activation, antibody production, cytokine secretion and antigen cross-presentation mainly depending on their protein component via TLR2/MyD88 dependent manner." (PMID 23326458, 2013). "However, TLR4 and MyD88 expression were not correlated with other parameters such as tumor stages, nodal status, tumor size or tumor site." (PMID 22583829, 2012). "To study the effects of pardaxin on tumor functions, we performed a real-time RT-PCR analysis of caspase-3, caspase-7, caspase-8, caspase-9, Bax, Bcl-2, STAT2, ATF3, STAT3, SOCS3, IL-2, cathelicidin, TNF-α, MyD88, NF-κB1, p65, IFN-β1, IFN-γ, IL-1β, IL-6, IL-7r, and IL-10." (PMID 23015777, 2012). "In the absence of MyD88 signaling, the activation of the pro-inflammatory innate immunity cells (such as M1-like macrophages) does not occur, the cytokine production is abrogated, the response is not polarized to a Th1 profile and the tumor cells are allowed to proliferate." (PMID 38835781, 2024). "We did not observe diminished expression of other immune sensors MAVS and MyD88 or downstream components of these immune pathways TBK1 and IRF3; suggesting that targeting of STING-specific immune responses may be an important strategy to facilitate tumor progression in HPV+ HNSCCs." (PMID 38147007, 2024). "Regarding tumour mutational burden (TMB), CD36 was significantly positively correlated only in LUAD, while showing a significant negative correlation in THCA and STAD; MYD88 was significantly positively correlated with TMB in BLLCA, ESCA, STAD, but the opposite was found in CHOL, OV and UVM." (PMID 38742843, 2024). "However, the immunogenicity of tumor cells exposed to ICD-inducer is lost in mice presenting with genetic defects in TLR4 or MYD88, suggesting not all tumor cells will ultimately elicit an antitumor-specific T-cell immunity in the presence of ICD-inducer such as chemotherapy or radiotherapy." (PMID 37142279, 2023). "Interestingly, we found that MYD88 expression levels were significantly elevated in subtype C1 (p < 0.05), and thus, we believe that MYD88L265P might contribute to the activation of the TLR signalling pathway in subtype C1 and induce tumour development." (PMID 36276947, 2022).
tumor (continued). "We showed that the circCUL2/miR-203a-5p/MyD88/NF-κB/IL6 axis contributes to the induction of iCAFs and established a distinct fibroblast niche for PDAC progression, which could help the development of strategies that selectively target tumor-promoting CAFs in PDAC." (PMID 35189958, 2022). "However, these authors mainly focused their work on the synergy between MYD88 and the catalytic subunit HOIP which increases LUBAC ligase activity that in turns promotes NF-κB canonical activation; only four so-called CD19-cre-MYD88LP have been studied at the tumor stage." (PMID 34017329, 2021). "They found a large-sized and non-dividing CD44+ ALDH1+MYD88+ subtype of OCs, which exhibits several properties of CSCs, including the capacity to generate tumors in immunodeficient mice, the capacity of functioning as tumor vascular progenitors, and chemoresistance." (PMID 32899775, 2020). "Given to a tumor consists of heterogeneous cell populations, we could easily replace the binding domain of CXCR4-KLA with other ligands to target other CSCs that express different cell-surface biomarkers such as CD133, CD44, CD117, and MyD88 of OVC in the future." (PMID 28196146, 2017). "Compared to tumors from mice that were not exposed to Paclitaxel treatment (primary tumor), tumors from recurrent disease after treatment with Paclitaxel (early recurrent tumor) had higher levels of genes associated with stemness such as ALDH1, KLF4, MYD88, NANOG, and OCT-4." (PMID 24403249, 2013). "It is not yet clear whether TLR4 and MyD88 are involved in tumour initiation." (PMID 20145615, 2010). "MC38 tumor cells were s.c. implanted into WT or Tlr4−/− or Myd88−/− C57BL/6 mice, and tumor-bearing mice were treated with β-lap with or without anti-HMGB1Ab." (PMID 31324798, 2019). "TRAM, specifically involved in the MyD88-independent signaling pathway, had no obvious changes with treatment of APS both in RAW 264.7 cells and in MyD88+/+ tumor-bearing mice." (PMID 28303957, 2017). "Il10−/−; Myd88−/− mice treated with AOM displayed reduced expression of Il12p40 and Tnfα mRNA and showed no signs of tumor development." (PMID 19551144, 2009). "Importantly, we found that DS-induced IFN-I activation in tumor cells is dependent on TBK1; silencing TBK1, but not MAVS, STING, or MyD88, abolished DS-mediated IFN-I activation." (PMID 40625660, 2025). "However, the specific MyD88-upstream receptor was not identified, whereas several TLRs and IL-1R tested did not appear to be involved in BCG-induced MB49 tumor control." (PMID 38835781, 2024). "Interestingly, only the spleen cells isolated from tumor-bearing WT mice previously treated with BCG and restimulated in vitro with BCG were capable to produce IFN-γ, that was abrogated in the absence of MyD88." (PMID 38835781, 2024). "While our study is consistent with previous studies that investigated TLR4 expressed on cancer cells which report the involvement of TLR4/MyD88 in tumor progression, the involvement of the TLR4/TRIF pathway in tumor progression is not well-supported in the literature." (PMID 36232715, 2022). "In addition, the LLC tumor-bearing mice in which endogenous macrophages were depleted by clodronate liposomes were intratumorally injected with WT, TLR4−/−, or MyD88−/− BMDMs primed or not with PcrV." (PMID 34900687, 2021). "Higher MyD88 expression is not a major prognostic determinant in GCC, but it may relate to the tumor cell differentiation." (PMID 32477927, 2020). "In contrast, docetaxel-induced TNF-α release from tumor cells appears to be independent of MyD88, since we observed strong docetaxel-induced increases in soluble TNF-α levels in A2780 cells that lack detectable MyD88 expression." (PMID 28915246, 2017). "Knockdown of neither TRIF nor MyD88, both of which are adaptor proteins involved in TLR family-mediated innate immune responses, apparently affected reovirus-induced IFN-β production in any of the tumor cell lines examined except HepG2 cells." (PMID 25866783, 2015).
tumor (continued). "Therefore current evidence suggests that paclitaxel may in fact be disadvantageous in patients whose tumours contain MyD88 positive EOC cells, despite retaining its cytotoxic effects in MyD88 negative cells." (PMID 24977712, 2014).
cancer (218 papers, 2010 to 2026). A tumor composed of atypical neoplastic, often pleomorphic cells that invade other tissues. "Elevated levels of MyD88 expression are associated with heightened activity in key metabolic pathways that are essential for cancer metabolism, including those involved in the turnover of amino acids, carbohydrates, lipids, and nucleic acids." (PMID 39744584, 2025). "The cancer driver mutation L265P MyD88 is found in approximately 30% of cases in the activated B cell-like subgroup of diffuse large B cell-like lymphoma (ABC DLBCL)." (PMID 39868594, 2025). "Recently, an increasing number of studies have shown that MyD88-driven cytokines are closely associated with cancer." (PMID 38785969, 2024). "MYD88 activating mutations were shown to result in the aberrant proliferation of multiple types of cancer cells." (PMID 37749630, 2023). "Previous findings have demonstrated that MyD88 and its related signaling pathways play crucial roles in the progression and development of cancer-associated cells." (PMID 37822929, 2023). "At last, we performed the analysis about association between ICD biomarker MYD88 and cancer properties to verify the role of this ICD related risk signature we constructed." (PMID 36248827, 2022). "There is an imminent need for the introduction of newer assays that can further improve the sensitivity of identifying MyD88 mutation in cancer cells seen in the vitreous." (PMID 35158867, 2022). "A spontaneous and sustained activation of MyD88-mediated via NF-κB signaling is associated with inflammation-induced cancer." (PMID 33834387, 2021). "There is evidence that stromal and cancer-associated fibroblasts promote tumorigenesis via TLR4/MyD88 signaling." (PMID 35048056, 2021). "Nuclear factor κB is the important signaling molecule downstream of MyD88 and data on how MyD88 deficiency affects carcinogenesis involved the role of NF-κB in cancer." (PMID 32477927, 2020). "Myd88 is known to facilitate TLR mediated signaling of various damage-associated molecular patterns (DAMPs) in certain instances of wounding or cancer (see45–47 for recent reviews)." (PMID 30291253, 2018). "As suggested, the conformational dynamics of cancer-associated MyD88-TIR domain mutant L252P seem to allosterically tilt the landscape toward homo-oligomerisation in vitro, which would propagate a signal independent of the TLR receptor activation." (PMID 30583727, 2018). "Previous reports have shown that MyD88 contributes to tumorigenesis in many inflammation-associated cancer models." (PMID 28662055, 2017). "Consistent with involvement in these inflammatory pathways, MyD88 signaling has been associated with cancer progression, which stems from the understanding that inflammation is linked to cancer promotion." (PMID 28201999, 2017). "The high expression of MyD88 was significantly associated with cancer histology (P=0.0333) and liver metastasis (P=0.0054) and potentially related to TNM stage (P=0.0745)." (PMID 20145615, 2010). "Targeting MyD88 or its associated signaling pathways might offer a potential approach to increase cancer cell sensitivity to treatment and improve therapeutic outcomes." (PMID 38347830, 2024). "For instance, evidence suggests that CD36 may contribute to the metastatic process in several cancers, while MYD88 mutations have been implicated in the dysregulation of immune responses in cancer pathogenesis." (PMID 38742843, 2024). "Furthermore, the cancer-causing mechanism was linked to the MyD88-dependent stimulation of IL-6 production by Kupfer cells (macrophages) in the chemically damaged liver by observing that the sex bias in HCC development was abrogated in MyD88−/− mice." (PMID 35406728, 2022). "We speculate that, similar to cancer models, inflammation associated with F. nucleatum is likely dependent on MyD88 signaling." (PMID 33653893, 2021).
cancer (continued). "However, the data are contradictory, which indicate that the role of MyD88 in the development and progression of inflammation-associated cancers is complex." (PMID 28201999, 2017). "MyD88 has been shown to contribute to tumorigenesis in many inflammation-associated cancer models." (PMID 28662055, 2017). "The Cancer Genome Atlas (TCGA) database was screened to identify BC-related mutations (apart from oncogenes), targeting, in particular, TLRs, the adaptor molecule MyD88, and the cGAS-STING (cyclic GMP-AMP synthase-stimulator of interferon genes) immune pathway." (PMID 40778061, 2023). "In addition to their role in inflammation-induced cancers, it was demonstrated that 29% of activated B-cell-like subtype of diffuse large B-cell lymphomas harboured an amino acid substitution, L265P, in the MYD88 TIR domain, and that some rare cases had other mutations." (PMID 33597599, 2021). "However, the MYD88 rs6853 variant was associated with significantly reduced risk of cognitive dysfunction, identifying MyD88 signalling pathways as a potential focus for predicting and reducing the burden of cognitive dysfunction in cancer patients." (PMID 26332828, 2015). "Activation of either or both TLR2 and TLR4, and further downstream signaling via the MyD88 and NFκB pathway, has been shown in other cancerous tumors as well as mycotic keratitis." (PMID 40725140, 2025). "In summary, SsnB exerts its anti-cancer effects by downregulating MyD88, p-ERK, and p-NFκB signaling, along with suppressing the pro-inflammatory cytokines TNF-α, IL-1β, and IL-6." (PMID 40143078, 2025). "The PI3K‐Akt signaling pathway plays a key role in cell growth, survival, metabolism, and motility, and activation of its related genes (MYD88, IL7R, MYB, CSF1) has been implicated in the initiation and progression of several cancers." (PMID 41328768, 2025). "AMK polysaccharide • Enhanced phagocytosis by BMDMs• Activated expression and secretion of immunomodulatory factors (IL-6, IFN-λ, TNF-α, and NO) in BMDMs through TLR4 and MyD88The TLR4/MyD88 pathway plays a vital role in anti-cancer effects of AMK." (PMID 40144663, 2025). "In contrast, MYD88, was the third most prevalent mutation in UCEC across 30 types of cancer, with a frequency of roughly 1.7%." (PMID 39475915, 2024). "On the other hand, MYD88 showed upregulated expression in several types of cancer, mainly including BRCA and ESCA." (PMID 38742843, 2024). "A comprehensive understanding of MyD88’s role in drug resistance is crucial for devising strategies to overcome resistance and enhance the effectiveness of cancer treatment." (PMID 38347830, 2024). "This further demonstrates the importance of TLR/MyD88 in regulating cancer cell proliferation and tumorigenesis." (PMID 38785969, 2024). "A comprehensive understanding of MyD88’s mechanisms in metastasis aids in devising effective strategies to inhibit cancer spread, thereby enhancing patient prognosis." (PMID 38347830, 2024). "MYD88, however, showed a significant positive correlation with checkpoint expression in all cancers, especially in KICH." (PMID 38742843, 2024). "Therapy with GLP-1 RA reduced ferroptosis and systemic/myocardial levels of NLRP-3, MyD88, IL-1, IL-6 and IL-18, supporting their use in cancer patients treated with anthracyclines and ICIs." (PMID 39457081, 2024). "The activation of the unfolded protein response (UPR) in skeletal muscle during cancer cachexia is facilitated by TLR/MyD88; in turn, the targeted removal of MyD88 reduces the muscle atrophy induced by LLC tumors in mice." (PMID 38334644, 2024). "Despite several challenges and complexities, targeting MyD88 is a promising avenue for improving cancer treatment and has the potential to revolutionize patient outcomes." (PMID 38785969, 2024). "Numerous natural and synthetic products have demonstrated anti-inflammatory and anti-cancer activities that target MyD88." (PMID 38785969, 2024).
cancer (continued). "MyD88 is a molecular orchestrator with multifaceted implications for cellular processes central to cancer metastasis." (PMID 38347830, 2024). "Our findings revealed a significantly higher expression of MYD88 in cancer tissues compared to normal tissues (p < 0.001)." (PMID 39065761, 2024). "As exhibited in different cancer model systems, MYD88 directs innate immune signalling through the TLR members (except TLR3) and the IL-1 family and can function doubly in pro- and anti-tumorigenic responses." (PMID 38256152, 2024). "The clonally unrelated RT, RT-1 which harbors a GC phenotype, showed the presence of MYD88, a CLL driver mutation, as well as mutations in genes implicated in cancer pathogenesis, TET2 and KMT2D, which have also been seen in RT." (PMID 39246801, 2024). "Regarding the microenvironment, both CD36 and MYD88 showed a significant positive correlation with stromal score, immune score and overall microenvironment score in various cancers." (PMID 38742843, 2024). "In human cancer, the MyD88 protein serves as a link between immune signal transduction from TLR/IL-1R and the Ras carcinogenic signaling pathway." (PMID 38785969, 2024). "Previous studies on CIRP as a modulator of inflammation in cancer have revealed that CIRP can act as a damage-associated molecular pattern (DAMP) and stimulate MyD88-NFκB and its subsequent cytokine release via Toll-like receptor 4 (TLR4) binding." (PMID 38397942, 2024). "BCG heterologous immunological memory has been also related as a possible mechanism involved in cancer control, but the role of MyD88 in trained immunity and cancer is still an important scientific gap to be addressed." (PMID 38835781, 2024). "Other research has led to the discovery that T6167923, LM9, 4210, LM8, M20, and C17 exert anti-inflammatory, anti-cancer, and anti-viral effects by inhibiting the formation of MyD88 oligomers and reducing the production of inflammatory and fibrotic factors." (PMID 38785969, 2024). "The expression of MyD88 in malignant tumors significantly surpasses that in adjacent normal tissue and benign tumors." (PMID 38347830, 2024). "Considering that Myd88 plays a cancer promoting role in various types of tumors, and it has also been reported in lymphatic cancer (Shiratori, Itoh & Tohda, 2017)." (PMID 37953776, 2023). "For example, MyD88 has been shown to promote to the proliferation, migration and invasion of cancer cells via MyD88/NF-κB/AP-1 signaling." (PMID 37389186, 2023). "Strikingly, we found that MYD88 was identified to associate with OS and progression free interval (PFI) in a range of cancer." (PMID 37456890, 2023). "Because multiple cell types within tumors utilize TLRs and MyD88 to respond to adjuvants released by cancer cells, we first sought to identify which cell types were associated with MYD88 expression in the TCGA PAAD cohort." (PMID 37244938, 2023). "TLRs, except for TLR3, mediate the downstream signaling through MyD88, a adaptor protein that ubiquitously expressed in all the immune cells and several cancer tissues." (PMID 37822929, 2023). "The apoptosis caused by LPS plus SM-164 is blocked by toll-like receptor 4 (TLR4) or MyD88 inhibitor, which inhibits LPS-induced TNFα production by the cancer cells." (PMID 36119107, 2022). "To determine how MyD88 mediates LPS-induced cancer cell survival and apoptosis in the presence of an IAP antagonist, we analyzed the expression pattern of the related proteins." (PMID 36119107, 2022). "MyD88 inhibitor, 4210, also slightly reduced TNFα levels in the culture medium treated with LPS, suggesting that LPS stimulates TNFα production by the cancer cells through a MyD88-dependent pathway." (PMID 36119107, 2022). "In spontaneous models of tumorigenesis, mice with Col6a1+ fibroblast-specific deletions of Tlr4, Myd88, or Ptgs2 (encodes an enzyme important for PGE2 production) exhibit reduced cancer development." (PMID 36591258, 2022).